TWIST1 (twist family bHLH transcription factor 1)
Diseases named in the same sentence as TWIST1 in open-access papers (continued):
Sharing a sentence is not in itself a finding about the gene and the disease.
metastatic tumor (14 papers, 2011 to 2025). "Since high TWIST1 expression was associated with patient metastatic disease and the invasive edge of medulloblastoma xenografts, we investigated the possibility that TWIST1 can increase cell aggregation due to its ability to promote cell migration." (PMID 33948561, 2021). "About 81% of patients with metastatic disease (M+) showed high TWIST1 expression while only 54% of patients categorized as M0 at the time the primary tumor was resected showed high TWIST1 expression." (PMID 33948561, 2021). "Several studies have evaluated TWIST1 expression in primary tumors and revealed a correlation between TWIST1 expression and metastatic disease." (PMID 25238494, 2014). "Importantly, TWIST1 up-regulation in the primary tumor had high correlation with the presence of metastatic tumors." (PMID 25238494, 2014). "We found that the expression of TWIST1, SNAI1, ZEB1, hFN1, and MMP2 increased from healthy epithelial cells to primary and metastatic tumor cells, reaching the highest expression in mesenchymal cell models." (PMID 40332096, 2025). "Members of the Snail family of transcriptional repressors (e.g., SNAIL and SLUG) and other repressors of E-cadherin gene expression, such as ZEB1, ZEB2, and TWIST1, have been detected at EMT sites at the leading edge of metastatic tumors." (PMID 40490818, 2025). "(i) Representative images showing MYC/Twist1-HCC have histologic appearance of HCC and lung histology shows metastatic disease." (PMID 31933479, 2020). "Among them, ITGB1, TWIST1 and KRT6B are consistently up-regulated in metastatic tumors of both MB49 sub-clones." (PMID 31092844, 2019). "Furthermore, the expression of Snail, Twist1, and ZEB1 was higher in metastatic tumors than in non‐metastatic tumors." (PMID 40259641, 2025). "Twist1 is considered to be an inducer of EMT and a basic regulator of some metastatic diseases." (PMID 32974352, 2020). "Increased macrophage infiltration in MYC/Twist1 primary and metastatic tumors with no change in neutrophils or CD4 T cells infiltration was confirmed by IHC." (PMID 31933479, 2020). "Moreover, Snail, Twist1, and ZEB1 staining show increased intensity in metastatic tumors, which may contribute to lung metastasis in mice bearing subcutaneous tumors." (PMID 40259641, 2025).
nasopharyngeal carcinoma (14 papers, 2011 to 2025). A carcinoma arising from the nasopharyngeal epithelium. "In nasopharyngeal carcinoma, Twist1 is identified to play a central role in acquired resistance to paclitaxel." (PMID 28099910, 2017). "In nasopharyngeal carcinoma cells, down-regulation of Twist1 increases radio-sensitivity by inducing activation of the ERK pathway, but not the p-38 or JNK pathway." (PMID 28099910, 2017). "During generation of acquired resistance to paclitaxel, nasopharyngeal carcinoma cells showed upregulation of Twist1 at both the mRNA and protein levels and were also cross-resistant to vincristine." (PMID 22245869, 2012). "In conclusion, Src-1 and Twist1 is aberrantly up-regulated in nasopharyngeal carcinoma tissues." (PMID 30973923, 2019). "Evidence in the nasopharyngeal carcinoma cell line HNE1 revealed a downregulation of Twist1 may increase drug sensitivity of HNE1 to taxol by inducing apoptosis." (PMID 24805866, 2014). "However, the exact role of Src-1 and Twist1 in nasopharyngeal carcinoma (NPC) is uncertain." (PMID 30973923, 2019). "In hematopietic stem cells, for example, TWIST1 binds to the promoter of Gata2 and induces its transcription, while in nasopharyngeal carcinoma cells, GATA2 induces EMT by binding to the promoter of Twist1 and activating its expression." (PMID 32226439, 2020). "In this study, we found that Twist1 was expressed in nasopharyngeal carcinoma tissues but not in the adjacent normal tissues." (PMID 27793033, 2016).
pulmonary hypertension (12 papers, 2017 to 2025). Increased pressure within the pulmonary circulation due to lung or heart disorder. "Additionally, during EMT and also during EndMT associated with pulmonary arterial hypertension, HIFα directly induces the expression of TWIST1." (PMID 32226439, 2020). "TWIST1 also mediates hypoxia-induced pulmonary hypertension by endothelial-to-mesenchymal transition (EndMT) as well as by changing PDGFB expression in ECs." (PMID 34660572, 2021). "Recent studies also found the contribution of TWIST1 in vascular diseases like pulmonary hypertension, which may be due to promoting the proliferation of smooth muscle cell." (PMID 40267100, 2025). "We are not aware of any prior description of patients with therapy-refractory pulmonary hypertension in conjunction with a deletion of chromosome 7 involving TWIST1 and PHF14, and believe this to be an important differential diagnosis in neonates with this presentation." (PMID 28814329, 2017).
atherosclerosis (11 papers, 2016 to 2026). A disease characterized by the build-up of fatty material and calcium deposition in the arterial wall resulting in partial or complete occlusion of the arterial lumen. "More recently, genome-wide association studies have identified TWIST1 as a causal gene that increases risk for multiple vascular diseases, including atherosclerosis and hypertension." (PMID 41246007, 2025). "TWIST1 is a basic helix-loop-helix transcription factor that is activated by DF and promotes endothelial dysfunction and atherosclerosis, making it an attractive candidate for the DF-sensitive regulation of EVA1A." (PMID 36794585, 2023). "Further, endothelial-specific deletion of Gata4 or Twist1 reduces the lesion size in atherosclerotic mice indicating that the Gata4–Twist1–Snai1 pathway contributes to atherosclerosis." (PMID 34901211, 2021). "We see an upregulation of TWIST1 expression in SMCs in response to IL-1β, which is in agreement with the model of smooth muscle de-differentiation and phenotypic switching during atherosclerosis." (PMID 31917787, 2020). "The effects of modulating TWIST1 in vivo to potentially affect proliferation and calcification will likely yield new insights into the role of SMCs in atherosclerosis." (PMID 31917787, 2020). "Immunostaining for TWIST1 in normal carotid arteries and in areas of atherosclerosis show that low basal TWIST1 expression in medial SMCs was increased in carotid plaques." (PMID 31917787, 2020). "Thus, while constitutive loss of HDAC9 has been shown to protect from atherosclerosis in a mouse model and may be involved in regulating disease risk at this locus, our data link the rs2107595 haplotype with TWIST1 expression, suggesting a role for TWIST1 in human vascular disease." (PMID 31917787, 2020). "The expression and function of TWIST1 was studied in EC in both developing vasculature and during the initiation of atherosclerosis." (PMID 27245171, 2016). "In adult mammalian arteries, TWIST1 was expressed preferentially at atheroprone sites exposed to low shear stress where it promoted the development of atherosclerosis by inducing inflammation and EC proliferation." (PMID 27245171, 2016). "TWIST1 promoted atherosclerosis by enhancing inflammation, endothelial cell proliferation, and vascular permeability and by inducing endothelial-to-mesenchymal transition." (PMID 27245171, 2016). "Gene silencing in cultured EC and EC-specific genetic deletion in mice demonstrated that TWIST1 promoted atherosclerosis by inducing inflammation and enhancing EC proliferation associated with vascular leakiness." (PMID 27245171, 2016). "TWIST1 expression contributed to atherosclerosis by enhancing vascular inflammation and by driving endothelial cell proliferation and permeability." (PMID 27245171, 2016). "TWIST1 expression contributed to atherosclerosis by enhancing vascular inflammation and driving EC proliferation associated with vascular leakiness." (PMID 27245171, 2016). "It points out that targeting TWIST1 may offer a promising new therapeutic approach for slowing the progression of atherosclerosis in hypertension." (PMID 40109339, 2025). "Future work using in vivo models of atherosclerosis with SMC-specific TWIST1 overexpression or knockdown will be important for better understanding how TWIST1 alters expression of its downstream targets and contributes to lesion burden in the complex atherosclerosis environment." (PMID 41246007, 2025). "Nevertheless, we speculate that TWIST1 governs the expression levels of a large number of genes, and that by modulating gene expression levels in the arterial wall TWIST1 plays a key role in the development and progression of atherosclerosis and CAD." (PMID 35714152, 2022). "Thus, TWIST1 is a coordinator of vascular development and also contributes to the initiation of focal atherosclerosis in adult arteries." (PMID 27245171, 2016).
atherosclerosis (continued). "Given their roles in regulating inflammation and EC proliferation in response to low shear stress, we hypothesized that GATA4 and TWIST1 may influence the initiation of atherosclerosis." (PMID 27245171, 2016). "We suggest therefore that the behavior of EC at atheroprone sites is a reflection of an early developmental stage and that developmental genes including GATA4 and TWIST1 could be novel therapeutic targets in atherosclerosis." (PMID 27245171, 2016). "We suggest therefore that some mechanosensitive pathways operate both at atheroprone sites of adult arteries and in developing vessels and that developmental genes including TWIST1 could be novel therapeutic targets in atherosclerosis." (PMID 27245171, 2016). "TWIST1 is a basic helix-loop-helix transcription factor that is known to govern gene expression and multiple biological processes such as endothelial-to-mesenchymal transition, while also playing an important role in developmental processes and various disease states including atherosclerosis." (PMID 35714152, 2022). "TWIST1 is also involved in cellular senescence as well as epithelial/endothelial to mesenchymal transition (EMT/EndMT), which is involved in atherosclerosis." (PMID 39479393, 2024). "To determine whether TWIST1 expression could be induced in differentiated SMCs, and therefore be relevant in adult pathology as well as in development, we stimulated cells with interleukin (IL)-1β, an inflammatory cytokine upregulated during atherosclerosis disease progression." (PMID 31917787, 2020). "Genetic deletion of GATA4 or TWIST1 in EC reduced lesion area in the aorta, indicating that GATA4–TWIST1 signaling contributes to atherosclerosis." (PMID 27245171, 2016). "In the context of atherosclerosis, our data do not support previously reported findings that TWIST1 suppresses expression of traditional SMC differentiation markers." (PMID 41246007, 2025). "These alternate studies do not dispel the notion that HDAC9 is important for atherosclerosis and CAD, but rather, they suggest that this locus causes CAD by governing Twist-related protein 1 (TWIST1), rather than HDAC9." (PMID 35714152, 2022).
esophageal cancer (10 papers, 2011 to 2025). A primary or metastatic malignant neoplasm involving the esophagus. "It has also been proposed that downregulation of miR-186-5p promotes cell proliferation and invasion due to its effect on Twist1, and low levels of miR-186-5p have also been linked to other tumours such as colorectal and esophageal cancer." (PMID 34811506, 2022). "GSEA of gene expression profiles of the Twist1-high group indicated that Twist1 in esophageal cancer was very strongly associated with the gene signature of cancer-associated fibroblasts, cancer stroma, and even mesodermal development." (PMID 29029429, 2017). "TWIST1 expression has been reported to correlate with the downregulation of Claudin-4 in esophageal cancer tissues and in cell lines overexpressing TWIST147." (PMID 40204777, 2025). "There was also a very strong association between the Twist1-Prrx1-TNC PFL expression in CAFs and the patients’ poor prognosis in esophageal cancer (P < 0.001)." (PMID 30069061, 2018). "Bioinformatic analysis of mRNA expression data of esophageal cancer from TCGA revealed that gene sets of CAFs were highly enriched in Twist1-high ESCC." (PMID 29029429, 2017). "Next, we performed gene set enrichment analysis (GSEA) on a Twist1-high esophageal cancer group from the cohort of 196 esophageal cancers with TCGA data." (PMID 29029429, 2017). "Our results were also corroborated by bioinformatic analysis of gene expression profiles (RNA-SEQ) in esophageal cancer downloaded from TCGA, where there was a strong correlation between mRNA levels of Twist1 and CAF markers." (PMID 29029429, 2017). "Most curiously, gene sets of mesoderm development were also significantly enriched (NES = 1.63, FDR q-val = 0.027) in Twist1-high esophageal cancer." (PMID 29029429, 2017). "Because Twist1 was reported to induce the migration and invasion of esophageal cancer cells, we speculated that Twist1 expressing fibroblasts also increase Twist1 expression in esophageal cancer cells." (PMID 29029429, 2017). "Given that these CAF markers and Twist1 are predominantly expressed in stromal fibroblasts, the data from TCGA offer an additional source for insights into the functional significance of stromal Twist1 in esophageal cancer." (PMID 29029429, 2017). "Based on these data, it was expected that Twist1-expressing fibroblasts may enhance in vivo tumorigenicity of esophageal cancer cells." (PMID 29029429, 2017). "To validate these results with an independent data source and further investigate biological pathways active in Twist1-high ESCC, we analyzed normalized gene expression data for 196 esophageal cancers (RNA sequencing) downloaded from TCGA." (PMID 29029429, 2017).
head and neck cancer (10 papers, 2012 to 2026). A primary or metastatic malignant neoplasm affecting the head and neck. "Overexpression of TWIST1 is associated with poorer overall survival in head and neck cancer, while E2 expression is associated with improved outcomes in HPV-positive head and neck cancer (44, –, 46)." (PMID 33298572, 2020). "TWIST1 specifically acts as an essential downstream effector of HIF-1α in head and neck cancer, where its knockdown in HIF-1α-overexpressing cells reduces metastatic nodules in vivo." (PMID 41511366, 2026). "The results in these two HPV16-positive head and neck cancer cell lines support the model of E2 repressing TWIST1 gene expression." (PMID 33298572, 2020). "Our RNA-seq analysis predicted that TWIST1 was transcriptionally repressed by E2 and the entire HPV16 genome in N/Tert-1 cells; in addition, TWIST1 was also downregulated in HPV16-positive versus HPV16-negative head and neck cancer." (PMID 33298572, 2020). "Immunohistochemistry staining of Twist1, Jagged1, and KLF4 in 242 head and neck cancer patient samples showed there was significant correlation between Twist1, Jagged1, and KLF4." (PMID 26823670, 2016). "Bmi1 is regulated by Twist1 which is one of the epithelial mesenchymal transition inducers in head and neck cancer cells." (PMID 24312366, 2013). "E2 and TWIST1 levels inversely correlate in HPV16-positive head and neck cancer cell lines." (PMID 33298572, 2020). "Post-translational regulation of TWIST1 might also be mediated through mutated EGFR activation, indeed, in head and neck cancer, IL6 activation was recently shown to stabilize TWIST1 through CK2 phosphorylation." (PMID 22272264, 2012). "Here, we demonstrate that TWIST1 is transcriptionally repressed by E2 in N/Tert-1 cells and that TWIST1 is downregulated in HPV-positive head and neck cancer versus HPV negative." (PMID 33298572, 2020). "We demonstrate, in two HPV16-positive head and neck cancer cell lines (one that is E2 positive, one that is negative), that E2 expression inversely correlates with TWIST1 expression, which correlates with our observations in N/Tert-1 cells and TCGA data sets." (PMID 33298572, 2020). "Furthermore, we also examined the correlation between the expression of Twist1, Jagged1, and KLF4 in head and neck cancer patient samples." (PMID 26823670, 2016). "In head and neck cancer cell lines cultivated in a 3D matrix environment, the EMT status affected the cell morphology, stiffness, and invasiveness, and the knockdown of the EMT transcription factors (EMT-TFs) TWIST1 and SNAI1 was sufficient to modulate the intrinsic stiffness of these cancer cells." (PMID 38398085, 2024). "In addition, using our analysis of The Cancer Genome Atlas (TCGA) data, we observed a significant downregulation of TWIST1 in HPV16-positive versus negative head and neck cancers (HNSCCs)." (PMID 33298572, 2020).
renal cell carcinoma (10 papers, 2017 to 2024). "The polyclonal loss of miR-210 in renal cell carcinoma cells increased tumor growth in a xenograft model, and while detailed cellular phenotype and gene expression studies were not performed, TWIST1 was suggested as a contributing miR-210 target." (PMID 39737000, 2024). "Interestingly, in renal cell carcinomas (RCC), tECs Snai1 and Slug were downregulated, and Twist1 expression levels barely changed compared to kidney-derived nECs." (PMID 39095583, 2024). "Androgen receptors have been reported to be able to alter TWIST1 nonsense-mediated decay via lncRNA-TANAR and promote vasculogenic mimicry (VM) in renal cell carcinoma (RCC)." (PMID 38819232, 2024).
skin cancer (10 papers, 2015 to 2026). "The greater ability of 3-epiCA and MA to inhibit skin tumor promotion was associated with greater reduction of Cox-2 and Twist1 proteins and inhibition of activation (i.e., phosphorylation) of IGF-1R, STAT3 and Src." (PMID 26513295, 2015). "Furthermore, genetic deletion of even one TWIST1 allele blocks the malignant conversion from benign papilloma to invasive carcinoma in a DMBA/TPA skin cancer model." (PMID 41511366, 2026). "However, the greater ability of 3-epiCA and MA to inhibit skin tumor promotion was associated with greater reduction of Cox-2 and Twist1 proteins and inhibition of activation (i.e., phosphorylation) of IGF-1R, STAT3 and Src." (PMID 26513295, 2015). "The upregulation of TWIST1 expression has been found in skin cancer patients, such as melanoma squamous cell carcinoma, sharing a positive family history of recurrence." (PMID 40332096, 2025). "TWIST1, a pivotal transcriptional enhancer, is reportedly critical for the formation and invasiveness of both chemically and ultraviolet B–induced skin tumours in mice." (PMID 40768619, 2025). "This suggests that increased expression of TWIST1 plays a role in CTCL progression, and is consistent with the recent discovery that TWIST1 is involved in skin cancer initiation, maintenance and progression in a dose dependent manner." (PMID 32872487, 2020). "Regarding skin carcinoma, partial EMT, characterized by Twist1 expression without E-cadherin depletion, has been reported to be associated with the acquisition of invasive traits in SCC, although this process is downregulated in lymph node metastases." (PMID 32106476, 2020).